MELK (maternal embryonic leucine zipper kinase)
Diseases named in the same sentence as MELK in open-access papers (continued):
Sharing a sentence is not in itself a finding about the gene and the disease.
breast carcinoma (continued). "High MELK expression correlates with poor prognosis in breast cancers and MELK is included in three different multi-gene expression profiles that predict BC aggressiveness, prognosis, and therapy response in the clinical setting." (PMID 28235006, 2017). "FOXM1 is a transcription factor known to upregulate MELK in basal-like breast cancers and MELK inhibition has been reported to downregulate FOXM1 in other cancers." (PMID 28235006, 2017). "We treated a panel of breast cancer cell lines, including MDA-MB-468 and ZR-75-1 cells, with HTH-01-091 and other MELK inhibitors; despite our focus on basal-like breast cancers, we included luminal cell lines for comparison." (PMID 28926338, 2017). "It was previously believed that a gene called MELK was an addiction in certain types of breast cancer." (PMID 28337968, 2017). "Previously, we reported development of a potent MELK inhibitor (OTS167) that effectively abrogated MELK kinase activity and suppressed growth of human breast cancer cells and acute myeloid leukemia cells." (PMID 26871945, 2016). "MELK is specifically and frequently upregulated in various types of human cancer including breast cancer, brain tumors, prostate cancer, and acute myeloid leukemia." (PMID 26918358, 2016). "Overexpression of MELK has been detected in a variety of human tumors, including breast cancer, glioblastoma, prostate cancer, colorectal cancer, and acute myeloid leukemia." (PMID 26701722, 2016). "We previously investigated the suppression of breast cancer spheroid formation by pharmacological inhibition of MELK." (PMID 26918358, 2016). "Knockdown of MELK with shRNA (breast cancer cell line T-47D) resulted in decreased proliferation of cells both in vitro and in vivo." (PMID 25852826, 2015). "Increased MELK expression was detected in particularly aggressive subtypes of breast cancer such as basal-like breast cancer (BBC), and correlates with poor prognosis." (PMID 25852826, 2015). "The p value for this differential expression (4.6 × 10−54) places MELK in the top 1% overexpressed genes in breast cancer." (PMID 24844244, 2014). "Several studies have shown that down-regulation of MELK by treatment with siRNA significantly induced apoptosis in breast cancer cells and various types of brain tumor." (PMID 25365263, 2014). "Analyses of breast cancer patient data according to subtypes revealed a remarkable overexpression of MELK in BBC." (PMID 24844244, 2014). "While luminal A and normal-like subtypes displayed the lowest expression of MELK, basal-like breast cancers (BBC) showed the highest expression level of MELK among all subtypes (p<0.0001)." (PMID 24844244, 2014). "MELK was scored in our kinase library screen and is overexpressed in breast cancer, particularly in basal-like breast tumors." (PMID 24844244, 2014). "To investigate the mechanism underlying MELK overexpression in BBC, we first analyzed the copy number of MELK in breast cancer." (PMID 24844244, 2014). "Together, these data suggest that Melk is not essential for normal development and physiological functions in mice, providing compelling evidence for MELK as a highly selective target for therapeutic intervention of basal-like breast cancer." (PMID 24844244, 2014). "We first analyzed a set of breast cancer cell lines that mirror the molecular subtypes of clinical tumors, and found that the expression level of MELK is much higher in the cohort of 23 BBC cell lines than in the cohort of 24 luminal breast cancer cell lines." (PMID 24844244, 2014). "Gene amplification of MELK occurs in both primary tumors and human breast cancer cell lines, especially in ER-negative samples." (PMID 24844244, 2014). "Recent studies also show that MELK is frequently elevated in multiple human tumors such as prostate cancer, breast cancer, glioblastoma multiforme and medulloblastoma, and is correlated with a poor prognosis." (PMID 24885567, 2014).
breast carcinoma (continued). "In contrast, the relative uniform overexpression of MELK in basal-like breast cancer makes it a potential common target in an otherwise heterogeneous disease." (PMID 24844244, 2014). "Again, high expression level of MELK robustly correlates with metastasis in breast cancer patients (both p values<0.001, hazard ratios >2)." (PMID 24844244, 2014). "Further examination of tumor samples collected from hundreds of women in previous clinical studies revealed that MELK expression was increased in basal-like breast cancers and other breast cancer tumors that lack the usual hormone receptor targets." (PMID 24844244, 2014). "Given the heterogeneity of breast cancer, we analyzed MELK expression in different subtypes of breast cancer as defined by gene expression profiling." (PMID 24844244, 2014). "In breast cancer, MELK has been found to interact with Bcl-GL through its amino-terminal region and suppress apoptosis." (PMID 24885567, 2014). "MELK was found to be up-regulated in various types of cancer including breast cancer and glioblastoma." (PMID 25365263, 2014). "A recent study using a murine breast cancer initiation model indicated that ablation of Melk eliminates tumorigenesis in vivo; thus MELK is likely a therapeutic target not only for GBM but also for other cancers." (PMID 23404835, 2013). "An increase in MELK expression is described in more aggressive forms of astrocytoma, breast cancer, melanoma, and glioblastoma." (PMID 24185907, 2013). "Overexpression of MELK suppresses Bcl-G-induced apoptosis, which promotes mammary carcinogenesis and results in poor patient survival in breast cancer and glioblastoma multiforms." (PMID 24185907, 2013). "We then investigated the effect of OTSSP167 on the formation of mammosphere, one of the characteristics of breast cancer stem cells since MELK was reported as a key molecule for cancer stem-cell formation/maintenance." (PMID 23283305, 2012). "We previously reported MELK (maternal embryonic leucine zipper kinase) as a novel therapeutic target for breast cancer." (PMID 23283305, 2012). "Since MELK was reported to be overexpressed in other types of human cancer in addition to breast cancer, we examined the growth inhibitory effect of OTSSP167 on the growth of various cancer cell lines." (PMID 23283305, 2012). "The functionally inter-connected proteins Fau, Bcl-G and MELK play critical roles in the control of apoptosis that are central to breast cancer development and therapy." (PMID 19671159, 2009). "Expression of Fau, Bcl-G and MELK was measured by quantitative RT-PCR in breast cancer tissue and in matched breast epithelial tissue from the same patients." (PMID 19671159, 2009). "Our findings clearly suggest that MELK is overexpressed in both breast cancer specimens and cancer cell lines, and that its kinase activity possibly plays a significant role in breast cancer cell growth." (PMID 17280616, 2007). "The MELK gene (GenBank accession number NM_014791) was found to be one of the genes transactivated at a very high level in the great majority of the breast cancers examined." (PMID 17280616, 2007). "We found that down-regulation of MELK by treatment with siRNA significantly suppressed the cell growth of breast cancer, indicating its crucial role in the proliferation and tumorgenesis of breast cancer." (PMID 17280616, 2007). "In this study, we characterize the biological function of MELK and indicate that it would be a good candidate as a molecular target for breast cancer therapy, although there would be some concerns over intestinal adverse reactions." (PMID 17280616, 2007).
breast carcinoma (continued). "To investigate the biological functions of MELK in breast cancer cells, we searched for substrates of MELK in cancer cells by in vitro protein pull-down assays using wild-type MELK (WT-MELK) and kinase-dead MELK (D150A-MELK) recombinant proteins." (PMID 17280616, 2007). "The subsequent semi-quantitative RT-PCR analysis of the transcript confirmed the elevated expression of MELK in 11 of 12 clinical breast cancer specimens." (PMID 17280616, 2007). "Together, these findings suggest that MELK has an oncogenic role in not only breast cancers but also bladder cancers, bone cancers and small cell lung cancers." (PMID 17280616, 2007). "Suppression of MELK expression by small interfering RNA significantly inhibited growth of human breast cancer cells." (PMID 17280616, 2007). "We demonstrated by means of siRNA that knockdown of endogenous MELK expression results in growth suppression of breast cancer cells." (PMID 17280616, 2007). "Our data should contribute to a better understanding of breast carcinogenesis, and they suggest that MELK is a promising molecular target for breast cancer treatment." (PMID 17280616, 2007). "In this study, we report evidence indicating that MELK functions as a cancer-specific protein kinase, and that down-regulation of MELK results in growth suppression of breast cancer cells." (PMID 17280616, 2007). "Using accurate genome-wide expression profiles of breast cancers, we found maternal embryonic leucine-zipper kinase (MELK) to be significantly overexpressed in the great majority of breast cancer cells." (PMID 17280616, 2007). "Subsequently, we examined MELK expression in breast cancer cell lines by western blot analysis with anti-MELK polyclonal antibodies." (PMID 17280616, 2007). "Notably, we further investigated the inhibitory potential of its triterpenoids using in silico models targeting four key proteins associated with breast cancer (HPA, MELK, CK2α, and NUDT5)." (PMID 41237100, 2025). "As a member of the AMPK-related kinase family, MELK is overexpressed in various malignancies including breast cancer, hepatocellular carcinoma, and glioma, where it drives oncogenesis by regulating cell cycle progression, cancer stemness, and therapy resistance." (PMID 40709174, 2025). "Thus, we next decided to further investigate the impact of MELK on stem cell properties and metastasis in breast cancer." (PMID 40076867, 2025). "Therefore, to leverage MELK's role in breast cancer metastasis as a therapeutic target, we need to identify specific and potent MELK inhibitors." (PMID 37377604, 2023). "In addition, it is acknowledged that inhibiting MELK, as a pivotal gene in breast cancer, can reduce cell division by suppressing the expression of cyclin B and D170 and increasing the sensitivity of breast cancer tumors to chemo- and radiotherapy." (PMID 37231064, 2023). "Therefore, there remains a need to determine the role of MELK in modulating the tumor microenvironment, which is a critical component of breast cancer response to treatment." (PMID 37377604, 2023). "Because high MELK expression correlates with metastasis in patients with breast cancer and because the function of MELK in TNBC metastasis has not been investigated, we examined the effects of MELK knockdown on migration and invasion, the two key early processes of metastasis." (PMID 37377604, 2023). "We then evaluated MELK CNA by FISH in breast cancer cell lines." (PMID 35749404, 2022). "The data suggest the significant role of MELK in aggressive breast cancer and supporting further investigation of the MELK mRNA/protein level as a biomarker for identifying candidates who may benefit from MELK-targeted therapy." (PMID 35749404, 2022).
breast carcinoma (continued). "Understanding MELK aberrations, genetic mechanism(s) of MELK overexpression, as well as MELK status in breast cancer tissues could identify patients with aggressive TNBC/BLBC with poor prognosis." (PMID 35749404, 2022). "Our data showed that MELK copy number (CN) gains are associated with BLBC, indicating a potential role of CN gains and MELK overexpression as prognostic markers for patients with aggressive breast cancer." (PMID 35749404, 2022). "Collectively, the correlation of MELK gene copies with mRNA in breast tumors and cancer cell lines suggest that subtype-specific expression of MELK may be partly due to CNA in breast cancer." (PMID 35749404, 2022). "MELK gene copies and RNA expression in breast cancer cell lines." (PMID 35749404, 2022). "Furthermore, MELK is overexpressed in many cancers, such as breast cancer, glioma, and colon cancer, and plays a role in oncogenes in these cancers." (PMID 33431809, 2021). "As DEPDC1 is involved in cytoskeletal regulation and brain metastasis, MELK might be involved in brain metastasis of breast cancer via DEPDC1 regulation." (PMID 34285339, 2021). "MELK was also found to be upregulated in tumor-initiating cells isolated from a genetically engineered mouse model of breast cancer, indicating that MELK function might be required for breast carcinogenesis via the development and maintenance of CSCs." (PMID 34285339, 2021). "Moreover, by inducing the proapoptotic function of Bcl-GL, siRNA-mediated depletion of MELK expression significantly inhibits the growth of human breast cancer cells." (PMID 34285339, 2021). "MELK 8a treatment selectively suppresses MELK-positive MDA-MB-468 breast cancer cell growth." (PMID 34285339, 2021). "Then, we performed a series of experiments and verified the hypothesis that miR-145-3p was a key mediator in the PCDHB17P/miR-145-3p/MELK axis in breast cancer." (PMID 34350110, 2021). "In addition, we referred to GSEA and found that MELK expression was related to metastasis and angiogenesis, rescue assays confirmed that the PCDHB17P/miR-145-3p/MELK axis was involved in the migration, invasion, and angiogenesis of breast cancer." (PMID 34350110, 2021). "To confirmed whether PCDHB17P modulate breast cancer progression in a MELK-dependent manner, we transfected breast cancer cells stably overexpressing PCDHB17P with miR-145-3p mimics or si-MELK." (PMID 34350110, 2021). "Hence, these results from our study revealed that PCDHB17P/miR-145-3p/MELK/NF-κB formed a positive feedback loop in breast cancer cells." (PMID 34350110, 2021). "In addition, we identified that MELK was a direct target gene of miR-145-3p, which was higher expressed in breast cancer tissues than that in adjacent normal tissues." (PMID 34350110, 2021). "MELK acts as a potential therapeutic target for TN breast cancer and other aggressive malignancies." (PMID 32190687, 2020). "However, there were several contradictory studies that explored the function of MELK in basal-like breast cancer." (PMID 31428132, 2019). "It has recently been suggested that the anti‐proliferative effects of OTS167 on breast cancer cells are mediated through off‐target effects, as MELK‐knockout cell lines remained sensitive to the inhibitor; however, no such findings have been reported in other cancer types to date." (PMID 29437778, 2018). "In breast cancer cells, MELK suppressed long isoform of Bcl-G (Bcl-GL)-induced apoptosis." (PMID 29783958, 2018). "A number of publications suggest that MELK may play an important function in various cancer types, particularly in brain and breast cancers." (PMID 29437778, 2018). "In brief, the selective MELK inhibitors exhibited weak antiproliferative activities against both basal-like and luminal breast cancer cell lines in vitro, casting doubt on whether MELK inhibition affects viability." (PMID 28926338, 2017). "3-day antiproliferative activities of MELK inhibitors in a panel of breast cancer cell lines*." (PMID 28926338, 2017).
breast carcinoma (continued). "Furthermore, correlative studies have repeatedly identified MELK expression as a gene signature in breast cancer." (PMID 28926338, 2017). "MELK RNAi and small-molecule inhibitors of MELK block the proliferation of various cancer cell lines, and MELK knockdown has been described as particularly effective against the highly-aggressive basal/triple-negative subtype of breast cancer." (PMID 28337968, 2017). "We confirmed potent inhibition of several off-targets and were keen on reducing the inhibition of FRAP1(mTOR), PIK3CA, and CDK7, as these kinases drive proliferation in breast cancer, which would complicate the interpretation of MELK-dependent pharmacology if inhibited." (PMID 28926338, 2017). "Interestingly, MELK has been reported as a novel oncogenic kinase and a promising selective therapeutic target for basal-like breast cancer recently." (PMID 28489584, 2017). "For instance, various publications disagree over the cell cycle stage affected by MELK inhibition, while other publications disagree over whether receptor-positive breast cancer cell lines are sensitive or resistant to MELK inhibition." (PMID 28337968, 2017). "7-day antiproliferative activities of MELK inhibitors in a panel of breast cancer cell lines*." (PMID 28926338, 2017). "Furthermore, high levels of MELK expression correlate with poor prognoses in patients with breast cancer and glioma." (PMID 26701722, 2016). "Furthermore, elevated MELK expression was negatively correlated with 5-year survival rate, which is consistent with the prognosis for breast cancer, prostate cancer, and glioblastoma with elevated MELK expression." (PMID 26701722, 2016). "Highly expressed MELK revealed poor survival in luminal A/B molecular subtypes of breast cancer." (PMID 27454576, 2016). "Though further investigation is needed, our results suggest that MELK might be involved in brain metastasis of breast cancer through DEPDC1 regulation." (PMID 26918358, 2016). "More importantly, the comparison of MTT assays in parental adherent SCLC cells and LS-derived SCLC cells revealed that OTS167 more effectively suppressed the growth of the latter cells as MELK inhibition by siRNA or OTS167 on breast cancer cells reported previously." (PMID 26871945, 2016). "To elucidate biological function of MELK, we treated cancer cells, MDA-MB-231 (breast cancer cell line) and A549 (lung cancer cell line), in which MELK was highly expressed, with a MELK inhibitor OTS167, and examined morphological changes of these cancer cells." (PMID 26918358, 2016). "Together, these data indicate the MELK is selectively required for the oncogenic growth of BBC cells, and suggest that MELK inhibition could be an effective approach in treating basal-like breast cancer." (PMID 24844244, 2014). "Interestingly, while luminal breast cancer cells have a similar pattern of MELK expression during cell cycle, their MELK protein levels in the M phase are much lower than those of BBC cells." (PMID 24844244, 2014). "Thus our data on MELK provide important information for guiding the development of targeted therapies in basal-like breast cancer." (PMID 24844244, 2014). "To gain insights into the potential relevance of MELK overexpression in breast cancer, we asked whether MELK expression correlates with the status of disease." (PMID 24844244, 2014). "Together, these data show that MELK may serve as a prognostic indicator in predicting breast cancer patients' likelihood of metastasis and overall survival rate." (PMID 24844244, 2014). "We next asked if MELK expression also correlates with the survival of breast cancer patients." (PMID 24844244, 2014). "Notably, the expression levels of FoxM1 and MELK demonstrate a striking correlation across all breast cancer samples and subtypes examined." (PMID 24844244, 2014). "Thus, MELK is potentially a novel oncogenic driver of basal-like breast carcinoma and a promising target for small molecule-based therapeutic intervention." (PMID 24844244, 2014).